OGG1 (8-oxoguanine DNA glycosylase)
Diseases named in the same sentence as OGG1 in open-access papers (continued):
Sharing a sentence is not in itself a finding about the gene and the disease.
adenoma (11 papers, 2006 to 2024). A neoplasm arising from the epithelium. "Second, the OGG1 rs159153 SNP modified the association between smoking pack-years and adenoma risk (interaction pgene = 0.040, interaction ppathway = 0.517)." (PMID 23951112, 2013). "We also found that the OGG1 rs159153 SNP, located 5′-upstream of OGG1, modified the association between smoking and adenoma risk." (PMID 23951112, 2013). "On the other hand, mice-deficient in the DNA repair enzyme OGG1 spontaneously develop adenoma and carcinoma." (PMID 20040097, 2009). "Our analysis pinpointed OGG1 VUSes in two individuals: case LS-298 was compound heterozygous for two OGG1 missense variants, p.Ala330Val and p.Asn331Ser, and case F1001 with several primary carcinomas and adenomas was heterozygous for the OGG1 missense variant p.Leu259Phe." (PMID 38725616, 2024). "For instance, a study reported that OGG1 was upregulated in adenomas with severe dysplasia and adenocarcinomas compared to normal adjacent tissue." (PMID 36982562, 2023). "Macroscopically, no tumors were found in the non-treated control Ogg1+/+ mice, however, spontaneous development of lung nodules (hyperplasia and adenoma) was detected in the control Ogg1−/− animals." (PMID 28820464, 2017). "A correlation between PARP-1 and OGG1 proteins content was found in adenoma tissues (r = 0.5697) and tumor tissues (r = 0.3645)." (PMID 25526641, 2014). "It is therefore of interest to study and compare the expression of OGG1 in adenoma and carcinoma tissues." (PMID 16914027, 2006). "Interestingly, the number of cells positively stained for PARP-1 and OGG1 was lower in adenoma tissues than in cancerous ones, although the intensity of staining was much stronger in polyps than in cancerous tissues." (PMID 25526641, 2014). "When comparing expression levels in normal tissue, the levels for OGG1 and RAI from CRC cases were significantly lower compared to the cases with adenomas, P = 0.012 and P = 0.011, respectively." (PMID 16914027, 2006). "We have examined mRNA expression of two DNA repair genes, ERCC1 and OGG1 as well as the putative apoptosis controlling gene RAI, in normal tissues and lesions from 36 cases with adenomas (mild/moderat n = 21 and severe n = 15, dysplasia) and 9 with carcinomas." (PMID 16914027, 2006). "This might reflect increased 8-oxoGua elimination from DNA, which would be consistent with the significant increase in OGG1 and PARP-1 protein in adenoma and carcinoma tissues in relation to normal colon tissue of CRC patients." (PMID 25526641, 2014). "Other studies showed that mRNA levels of OGG1 and ERCC1 genes are significantly increased in colon lesions in the adenoma-carcinoma pathway, and that this increase was higher in severe lesions, namely severe adenomas and carcinomas, than in mild ones." (PMID 25526641, 2014). "For all three genes, ERCC1, OGG1 and RAI, a comparison of expression levels between normal colonic mucosa and lesions in all cases combined (adenomas and CRC) yielded significantly higher expression levels in lesions, 3.3-fold P = 0.005, 5.6-fold P < 3*10-5 and 7.7-fold P = 0.0005, respectively." (PMID 16914027, 2006). "Lungs of Ogg1 null mice were strongly affected by DMBDD initiation, which could be concluded from significant increases of lung adenocarcinoma incidence in DMBDD-treated Ogg1−/− male mice and incidences and multiplicities of adenomas and total lung tumors in Ogg1−/− males and females." (PMID 28820464, 2017). "Unfortunately, the material obtained from adenoma patients did not contain well distinguished normal colon tissue which could be seen in histological sections as marginal tissue, and would enable to measure PARP-1 and OGG1 proteins in adenoma and normal colon from the same patient." (PMID 25526641, 2014).
head and neck cancer (11 papers, 2009 to 2024). A primary or metastatic malignant neoplasm affecting the head and neck. "It has also been reported that disease progression is faster in patients with head and neck cancer when OGG1 activity is low, which indicates that a low OGG1 activity is associated with an increased risk of head and neck cancer." (PMID 37627097, 2023). "Low OGG1 activity is associated with aggressive characteristics and prognosis of head and neck cancer, as well as other types of cancer." (PMID 37627097, 2023). "Most importantly is that reduced activity of OGG1 is considered an established risk factor for various cancers such as lung and head and neck cancer." (PMID 19789535, 2009). "Our results suggest OGG1 and PARG play a fundamental role in the cellular response to CDD and indicate that targeting these enzymes could represent a promising therapeutic strategy for the treatment of head and neck cancers following high-LET radiation." (PMID 38368415, 2024).
hepatocellular carcinoma (11 papers, 2006 to 2025). A malignant tumor that arises from hepatocytes. "Furthermore, loss of heterozygosity (LOH) in Ogg1 was suggested to play an important role in the development of human hepatocellular carcinomas (HCC), being an early event in hepatocarcinogenesis." (PMID 28785378, 2017). "Hepatocellular carcinomas (HCCs) were found in PB-treated Ogg1−/− mice, while Ogg1+/+ animals developed only hepatocellular adenomas (HCAs) at the same rate." (PMID 28785378, 2017). "For example, OGG1 expression levels in patients with hepatocellular carcinoma (HCC) were higher than healthy individuals with correlations between OGG1 expression and both the initiation and progression phases of HCC." (PMID 39741341, 2025). "Based on RT-qPCR analysis of Orox A-treated hepatocellular carcinoma cells, significant increases in the mRNA transcript levels of NEIL1, OGG1, ATR, and ATM were observed." (PMID 41009509, 2025). "Decreased expression of Ogg1 and mitochondrial Ogg1 (mtOGG1) were reported with human HCC tissues and SNU (Seoul National University) human hepatoma cell lines, respectively." (PMID 28785378, 2017). "No hepatocellular carcinomas were apparent in DMBDD-treated Ogg1 knockout and wild type animals." (PMID 28820464, 2017).
prostate carcinoma (11 papers, 2011 to 2021). A carcinoma that arises from epithelial cells of the prostate gland. "Single nucleotide polymorphisms (SNPs) in the gene coding for 8-oxoguanine glucosylase (OGG1), a selective base excision repair enzyme for OG-lesions, are associated with cancer progression with evidence also for an association with prostate cancer." (PMID 21982398, 2011). "In hypothesis generating explorative analyses, we found indications that the association between serum selenium levels and prostate cancer risk was modified by genetic polymorphisms, in the OGG1 gene (rs125701) and MnSOD gene (rs2758331- linked to rs4880)." (PMID 21982398, 2011). "Similar to APEX1 SNPs, several SNPs in other DNA repair genes, specifically OGG1, LIG3, and XRCC1, were associated with prostate cancer among men taking finasteride." (PMID 35096612, 2021). "Except for one protective variant (MTHFR rs1801133) for prostate cancer (OR = 0.684, 95% c.i.=0.565–0.828), six of the seven variant (in MGMT, XRCC1, OGG1, ERCC2 and CASC8) showed risks for prostate cancer." (PMID 26967244, 2016). "During follow-up 208 men (10.2%) in the full cohort of 2045 and 126 of the 1005 genotyped men (12.5%) (OGG1), were diagnosed with prostate cancer." (PMID 21982398, 2011). "OGG1-rs1052133 and NOS3-rs1799983 were associated with risk of low-grade prostate cancer." (PMID 35096612, 2021). "The investigated SNPs in OGG1 per se did not influence the risk for prostate cancer on a statistically significant level." (PMID 21982398, 2011). "Our hypothesis generating results that serum selenium levels and the polymorphic genes OGG1 and MnSOD involved in the protection from oxidative stress, act concurrently in the defence of prostate cancer development are in accord with previous knowledge." (PMID 21982398, 2011). "A further study that measured DNA methylation in four oxidative stress-related genes identified a significant association of DNA methylation at one site in the promotor region of the 8-oxoguanine DNA glycosylase (OGG1) gene with overall cancer incidence and prostate cancer incidence." (PMID 30678711, 2019). "OGG1-rs1052133 was positively (CG/GG vs. CC: OR=1.32, 95% CI: 1.01-1.73) and NOS3-rs1799983 was inversely (per minor allele: p-trend=0.04) associated with risk of low-grade prostate cancer." (PMID 35096612, 2021).
Insulin resistance (10 papers, 2014 to 2024). Increased resistance towards insulin, that is, diminished effectiveness of insulin in reducing blood glucose levels. "Despite all these previous studies, there were, however, many gaps in knowledge regarding the tissue-specific mechanisms of how OGG1 deficiency leads to whole-body insulin resistance." (PMID 39596235, 2024). "The second novelty of our current work is that nuclear OGG1 is nonessential for insulin resistance phenotype, since specific reconstitution of mt-hOGG1 alone prevented HFD-induced insulin resistance in OGG1-deficient animals." (PMID 39596235, 2024). "OGG1-deficient (Ogg1-/-) animals display increased propensity to age-induced and diet-induced metabolic diseases, including insulin resistance and fatty liver." (PMID 31935236, 2020). "Mice deficient in 8-oxoguanine DNA glycosylase (the enzyme that performs base excision repair of DNA by cleaving 8-oxoG and other modified bases) were found to be prone to insulin resistance upon high-fat feeding." (PMID 30116482, 2018). "Since Ogg1-/- mice were previously shown to be prone to insulin resistance, we were interested in determining the effects of OGG1 deficiency on skeletal muscle metabolism and function." (PMID 28727777, 2017). "However, the tissue-specific mechanisms of how OGG1 deficiency leads to insulin resistance is unknown." (PMID 39596235, 2024). "Outstandingly, mt-hOGG1 expression alone was sufficient enough to prevent both hyperglycemia and insulin resistance in Ogg1-KO mice." (PMID 39596235, 2024). "This is the first evidence demonstrating that OGG1 contributes to HFD-induced insulin resistance in the liver." (PMID 39596235, 2024). "In prior experiments using cells in culture, several reports established a protective role for mitochondrial OGG1 in lipid-induced insulin resistance and apoptosis." (PMID 30700008, 2019). "We have shown previously that when placed on a HFD, Ogg1-/- mice proceed to develop severe insulin resistance and other features of the metabolic syndrome, including fatty liver." (PMID 28727777, 2017). "Given the primary role of increased hepatic gluconeogenesis in the pathogenesis of hyperglycemia in insulin resistance and type 2 diabetes, new drugs aimed at targeting OGG1 specifically to mitochondria may propose a novel form of treatment for metabolic disease." (PMID 39596235, 2024). "The results of the clamp study showed a strong trend of increased insulin resistance with lower glucose infusion rates and whole-body glucose turnover and glycogen synthesis in HFD-fed Ogg1-KO mice compared to HFD-fed WT mice." (PMID 39596235, 2024). "Consistent with the increased hepatic insulin resistance, HFD-fed Ogg1-KO mice showed increased whole-body insulin resistance phenotype as evidenced by an increase in insulin levels as well as in the results of ITT." (PMID 39596235, 2024). "Ogg1-KO/HFD mice had a strong trend toward lower glucose infusion rates during clamps when compared to WT mice fed an HFD, suggesting increased insulin resistance in Ogg1-KO/HFD mice." (PMID 39596235, 2024). "In the absence of efficient oxidative DNA repair, Ogg1-/- mice have increased mitochondrial fission markers and subsequently go on to develop insulin resistance." (PMID 28727777, 2017). "Our findings suggest that mt-hOGG1 but not nuclear OGG1 expression is crucial to prevent insulin resistance and provides a strong rationale to deliver hOGG1 and possibly other DNA repair enzymes into mitochondria as a new translational approach for treatment of insulin resistance." (PMID 39596235, 2024). "The exact mechanisms by which mt-hOGG1 protects against HFD-induced insulin resistance are unclear, however, based on the results of oxidative mtDNA damage analysis, we can propose that the OGG1 BER enzyme activity is involved since mt-hOGG1 prevented liver oxidative mtDNA damage in Ogg1-KO/Tg mice." (PMID 39596235, 2024).
Insulin resistance (continued). "Therefore, a reduction in mitochondrial content is not likely to be a contributor to insulin resistance in the Ogg1-/- model." (PMID 28727777, 2017). "As HFD-fed Ogg1-KO mice showed a big increase in fat mass, we do not know whether OGG1 expression in the liver directly influenced insulin resistance or whether these differences were secondary, possibly due to the differences in the body weight between the WT and Ogg1-KO mice on HFD." (PMID 39596235, 2024).
metabolic syndrome (10 papers, 2012 to 2025). A cluster of metabolic risk factors for CARDIOVASCULAR DISEASES and TYPE 2 DIABETES MELLITUS. "The DNA repair enzyme 8-oxoguanine DNA glycosylase-1 (OGG1) plays a key role in modulating inflammation and metabolic syndrome." (PMID 39796239, 2025). "The DNA repair protein 8-oxoguanine DNA glycosylase-1 (OGG1) has significant roles in the modulation of inflammation and metabolic syndromes." (PMID 36746968, 2023). "Since NEIL1 and OGG1 have very distinct substrate specificities in the repair of oxidized lesions, these similarities in phenotype with regard to the development of metabolic syndrome were completely unexpected." (PMID 23284747, 2012). "Mice lacking OGG1 (Ogg1−/−) developed features of metabolic syndrome, including increased adiposity, fatty liver, elevated triglycerides, and impaired glucose tolerance." (PMID 30845725, 2019). "Additionally, we previously reported that mice lacking OGG1 (Ogg1-/-) are prone to features of metabolic syndrome, including increased body weight and adiposity, fatty liver, elevated triglycerides, and impaired glucose tolerance." (PMID 28727777, 2017). "Conversely, in the absence of OGG1, a HFD led to accelerated development of several features of metabolic syndrome, including increased adiposity, hepatic lipid accumulation, and impaired glucose tolerance upon high-fat feeding." (PMID 23284747, 2012).
bladder cancer (8 papers, 2012 to 2023). "Our results indicated the association of the XPD 312Asp/Asn heterozygous genotype with an increased risk of bladder cancer, whereas the OGG1 326Ser/Cys heterozygous genotype has exhibited the protective effect." (PMID 26649138, 2016). "In our studies, the OGG1 (codon 326) heterozygous genotype decreased bladder cancer risk, especially in smokers with OR = 0.55 (0.34–0.89) (p = 0.014) and prevented high grade tumors as compared to neoplasms of low malignant potential." (PMID 26649138, 2016). "In the DMBDD-treated Ogg1−/− mice, main causes of death besides malignant lymphoma/leukemia were lung adenocarcinoma and skin/subcutis fibrosarcoma, while Ogg1+/+ animals died from malignant lymphoma/leukemia and urinary bladder carcinoma." (PMID 28820464, 2017). "Here we aimed to assess the associations of nineteen polymorphisms from seven DNA repair–associated genes (PRAP1, OGG1, APEX1, MUTYH, XRCC1, XRCC2 and XRCC3) with bladder cancer and their interactions in the disease in a Han Chinese population." (PMID 27153553, 2016). "The frequencies of OGG1 Ser326Cys (rs1052133), XRCC1 Arg399Gln (rs25487), XPD Asp312Asn (rs1799793), and ERCC6 Met1097Val (rs2228526) polymorphisms have been recently determined in the bladder cancer (BC) patients as compared with clinically healthy residents of Belarus." (PMID 26649138, 2016).
lung adenocarcinoma (8 papers, 2002 to 2020). A carcinoma that arises from the lung and is characterized by the presence of malignant glandular epithelial cells. "The causes of death of Ogg1−/− male mice were malignant lymphomas/leukemia, lung adenocarcinoma and fibrosarcoma, while Ogg1−/− female mice died due to the development of lymphoma/leukemia." (PMID 28820464, 2017). "In NNK-treated mice, incidence of lung adenocarcinoma was significantly higher in the Ogg1 deficient mice than the Ogg1 positive mice." (PMID 24281202, 2010). "This study investigated the association between OGG1 Ser326Cys polymorphism and risk of the lung adenocarcinoma for Japanese by a prevalent case-control study in Japan." (PMID 12164330, 2002). "Recently an association between lung adenocarcinoma risk and new OGG1 polymorphisms at exon 1 has been reported for Japanese20)." (PMID 12164330, 2002). "In conclusion, this study suggested that the association between OGG1 Ser326Cys polymorphism and the risk of lung adenocarcinoma was limited, if any, but that the Cys/Cys genotype might be associated with the poor prognosis." (PMID 12164330, 2002). "The present study was designed to evaluate the association between antioxidant gene polymorphisms (SOD rs5746136 and SOD rs4880; CAT rs769218; OGG1 rs1052133; and TXN2 rs4821494) and EGFR-mutated lung adenocarcinoma." (PMID 32937815, 2020). "Importantly, DMBDD caused significant increases of incidences and multiplicities of lung adenocarcinoma in Ogg1−/− males, liver tumors in Ogg1−/− males and females and colon tumors in Ogg1−/− male mice as compared to the Ogg1−/− controls." (PMID 28820464, 2017). "Furthermore, incidences and multiplicities of lung adenocarcinoma were higher in female Ogg1−/− mice of DMBDD group as compared to the DMBDD-treated wild type counterparts." (PMID 28820464, 2017). "Importantly, the earlier development of tumors in DMBDD-administered Ogg1−/− males and females, mostly malignant lymphomas/leukemias, lung adenocarcinoma and subcutaneous tumors (fibrosarcomas) was the reason for their earlier mortality." (PMID 28820464, 2017). "This suggests that OGG1 Ser326Cys polymorphism-smoking interaction was not marked in adenocarcinoma of the lung enough to be detected in our study." (PMID 12164330, 2002). "Significant increase of lung adenocarcinomas incidence was observed in DMBDD-treated Ogg1−/− male mice, but not in DMBDD-administered Ogg1+/+ animals." (PMID 28820464, 2017). "Interestingly, significant increase of lung adenocarcinoma incidence and multiplicity was found in DMBDD-administered Ogg1−/− male mice (35%, 0.5 ± 0.7/mouse, p < 0.01), but not in the wild type males (10%, 0.1 ± 0.3/mouse) as compared to corresponding controls of the same genotype." (PMID 28820464, 2017).
type 2 diabetes (8 papers, 2012 to 2024). "In the search bars, we typed the concepts of interest “Type II diabetes” and “OGG1”, to check if this association was enriched in DES-ROD." (PMID 32308806, 2020). "In further support for a role for OGG1 in metabolic dysfunction, the Ser326Cys OGG1 polymorphism has been recently reported to be associated with Type II diabetes in both a Japanese and Mexican American population." (PMID 23284747, 2012). "Our findings are in agreement with previous report indicated increase of mitochondrial OGG1 in humans with type 2 diabetes." (PMID 23342074, 2013).